MED18 (mediator complex subunit 18)
Description:
Component of the Mediator complex, a coactivator involved in the regulated transcription of nearly all RNA polymerase II-dependent genes. Mediator functions as a bridge to convey information from gene-specific regulatory proteins to the basal RNA polymerase II transcription machinery. Mediator is recruited to promoters by direct interactions with regulatory proteins and serves as a scaffold for the assembly of a functional preinitiation complex with RNA polymerase II and the general transcription factors.
Synonyms: FLJ20045; p28b; SRB5
Tractability: Small molecule: a structure with a bound ligand is known. PROTAC: ubiquitination databases record sites on it; its protein half-life has been measured.
Gene: Protein-coding gene on chromosome 1 (28,329,002 to 28,335,965, forward strand). Ensembl gene ENSG00000130772.
Subcellular location: Nucleus
Subcellular location (Human Protein Atlas): Nucleoplasm
Pathways (Reactome):
Developmental Biology: Transcriptional regulation of white adipocyte differentiation
Disease: RSV-host interactions
Metabolism: PPARA activates gene expression
Gene Ontology:
Molecular function: protein binding; transcription coregulator activity
Biological process: positive regulation of transcription elongation by RNA polymerase II; positive regulation of transcription initiation by RNA polymerase II; RNA polymerase II preinitiation complex assembly; regulation of transcription by RNA polymerase II
Cellular component: core mediator complex; mediator complex; nucleus; nucleoplasm
Genetic constraint (gnomAD): Loss-of-function variants: 8 observed, 12.56 expected, observed/expected ratio (o/e) 0.64, 90% interval 0.37 to 1.15. The upper end of that interval is the gene's LOEUF score, 1.15, which puts it in group 5 of 6, group 1 being the genes least tolerant of losing a copy. Missense variants: 214 observed, 290.21 expected, observed/expected ratio (o/e) 0.74, 90% interval 0.66 to 0.83. Synonymous variants: 87 observed, 96.86 expected, observed/expected ratio (o/e) 0.9, 90% interval 0.75 to 1.07.
Homologues: Orthologues: chimpanzee MED18 (100% identical), macaque MED18 (99% identical), dog MED18 (99% identical), guinea pig MED18 (99% identical), mouse Med18 (99% identical), pig MED18 (99% identical), rat Med18 (90% identical), zebrafish med18 (81% identical), Drosophila melanogaster MED18 (52% identical), Caenorhabditis elegans mdt-18 (32% identical).
Diseases named in the same sentence as MED18 in open-access papers:
MED18 is named in the same sentence as 12 diseases in open-access papers, as found by Europe PMC text mining. Sharing a sentence is not in itself a finding about the gene and the disease. The quoted sentences say what the papers report.
gastric cancer (8 papers, 2019 to 2026). A primary or metastatic malignant neoplasm involving the stomach. "For instance, SNHG3 promotes gastric cancer progression through regulating neighboring mediator subunit 18 (MED18) gene methylation by binding to enhancer of zeste homolog 2 (EZH2)." (PMID 33292213, 2020). "The anticancer effect of MED18 occurs downstream of SNHG3 signaling in gastric cancer, which may imply its widespread mode of action in other cancers, and deserves further study." (PMID 33292213, 2020). "In gastric cancer, SNHG3 binds to EZH2 and epigenetically silence MED18 (Mediator Complex Subunit 18) expression." (PMID 32318335, 2020).
virus infection (2 papers, 2020 to 2024). "Whereas MED18 is considered a susceptibility factor, MED25 is required for defense against virus infection." (PMID 38245701, 2024). "Defense marker gene expression profiling of mock- and virus-inoculated plants showed that med18 and med25 mutants exhibited an upregulated SA pathway upon virus infection at 2 dpi for all viruses tested." (PMID 32194589, 2020). "MED18 is required for normal virus infection, while MED25 is important for defense against virus infection." (PMID 32194589, 2020). "The results obtained from this study confirmed our hypothesis that med18 mutants would be resistant to viral infection based on their defective JA and increased SA signaling, therefore establishing a firm role of MED18 for normal virus infection." (PMID 32194589, 2020). "This study can help to understand how plants interact with viruses and assist in establishing the pathways, including the roles of Mediator subunits MED18 and MED25, that were found to be required for normal virus infection and defense against viruses, respectively." (PMID 32194589, 2020).
dwarfism (1 paper, 2021). "The mutation in MED17, MED18, or MED20 resulted in dwarfism, delayed flowering, and reduced fertility." (PMID 33868352, 2021).
fungal infection (1 paper, 2021). "Therefore, both MED18 and NRPD2a may promote plant resistance to necrotrophic pathogens by acting as negative regulators of SA signaling but positive regulators of JA and ET signaling during response to the fungal infection." (PMID 34691090, 2021).
Fusarium infection (1 paper, 2017). "In support of our results presented here, an accompanying paper describe that both med18 and med20 mutants show a strong level of resistance to Fusarium infection in Arabidopsis." (PMID 28640868, 2017).
leiomyoma (1 paper, 2024). A well-circumscribed benign smooth muscle neoplasm characterized by the presence of spindle cells with cigar-shaped nuclei, interlacing fascicles, and a whorled pattern. "MED12 mutation-negative leiomyomas display copy number alterations in several other mediator complex subunits, such as MED18, MED8, CDK8, and the long non-coding RNA, RNA340 (CASC15)." (PMID 38279317, 2024).
tumor (5 papers, 2019 to 2026). "Transient knockdown of MED18 in SNHG3-deficient cells completely rescued the tumor suppressive phenotypes in GC cells." (PMID 31534128, 2019). "Studies have also reported that p27 inhibited promoter transcription of target genes, such as AURKA and MED18, which are closely related to the poor tumor prognosis." (PMID 34617876, 2021). "Taken together, our results demonstrated the anti-tumor activities of MED18 in GC cells via suppression of cell proliferation, migration and invasion." (PMID 31534128, 2019). "The predominance of MED18 in exerting oncogenic activity of SNHG3 was validated by the rescue assay as well, wherein co-knockdown of MED18 significantly reversed the tumor suppressing function elicited by SNHG3-silencing." (PMID 31534128, 2019).
infection (3 papers, 2020 to 2024). The state of being infected such as from the introduction of a foreign agent such as serum, vaccine, antigenic substance or organism. "Taken together, these results strongly suggest that mutations of MED18 and NRPD2a led to enhanced SA signaling but compromised JA signaling in response to infection by a necrotrophic fungal pathogen." (PMID 34691090, 2021). "Pathogen infection altered more than 6644, 6162, and 8697 genes in WT, med18 and nrpd2a mutants, respectively." (PMID 34691090, 2021). "Taken together, the KEGG analysis supports the finding from the GO enrichment analysis that a substantial number of genes involved in defense-related pathways were altered in expression in both the med18 and nrpd2a mutants in response to infection by Botrytis." (PMID 34691090, 2021). "Infection with all viruses exhibited clear growth reduction in plants, with visible symptoms being strongest in med25 mutants and weakest in med18 mutants." (PMID 32194589, 2020). "Mediator subunits MED8, MED15, MED16, MED18, MED20, MED25 and CDK8 were identified as important for diverse types of infection responses." (PMID 38514763, 2024).
cancer (2 papers, 2019 to 2026). A tumor composed of atypical neoplastic, often pleomorphic cells that invade other tissues. "We selected six DplUSE-containing genes (KIF20A, EXT2, CLDN12, MBNL2, MED18, DKC1) from the 31 orthologous genes identified by the bioinformatic script that are common to human, mouse, and zebrafish and that have a relevant physiological function in malignant neoplasms." (PMID 41505098, 2026).
MED18 also shares sentences with these, for which no sentence is quoted: colorectal cancer (1 paper); glioma (1); head-neck squamous cell carcinoma (1).